BCL6 (BCL6 transcription repressor)
Diseases named in the same sentence as BCL6 in open-access papers (continued):
Sharing a sentence is not in itself a finding about the gene and the disease.
lymphoma (continued). "Here, we will illustrate how NetAct infers TF activity on two cases of microarray KD experiments—one case for shRNA KD of FOXM1 and shRNA KD of MYB in lymphoma cells (GEO: GSE17172), and another case for KD of BCL6 on both OCI-Ly7 and Pfeiffer GCB-DLBCL cell lines (GEO: GSE45838)." (PMID 36575445, 2022). "High-grade large B cell lymphomas with concurrent MYC and BCL2 (or BCL6) translocations, previously known as double-hit (DHL)/triple-hit lymphomas, represent a rare category of tumors that is now recognized as a separate provisional entity in the revised WHO classification." (PMID 34456919, 2021). "Differently from tumors with an immunohistochemical expression of MYC and BCL2 (double expressors), aggressive B-NHLs harboring MYC and BCL2 or MYC and BCL6 rearrangements—when identified with FISH—present an even more aggressive behavior, and are also referred to as double-hit lymphoma." (PMID 34943410, 2021). "Furthermore, the increased detection of genetic aberrations frequently observed in B-cell lymphomas, including BCL2, BCL6, IGH, and MALT1 translocations, should promote the development of lymphoma gene panels for BALF in the era of next-generation sequencing." (PMID 34873224, 2021). "Currently, aggressive B-cell lymphomas with a combined MYC- and BCL2 and/or BCL6 translocations (so-called double-hit or triple-hit, DH/TH lymphomas) are classified as a separate entity, irrespective of morphological features." (PMID 34099699, 2021). "This category of double- or triple-hit lymphomas only comprises translocations involving MYC and the two other genes; hence, lymphomas expressing MYC with BCL2 and/or BCL6 (according to immunochemical assessments) but that lack translocations are not encompassed by the definition." (PMID 35096627, 2021). "BL is derived from a germinal center derived lymphoma, exhibiting BCL6, CD10, CD19, CD20, CD22, and CD79a expression and lacking CD5, BCL2, TdT, and, typically, CD23." (PMID 34283060, 2021). "Using FISH, 4 separate assays (BCL2,-BA (break-apart), BCL6-BA, MYC-BA, MYC-IGH-F(fusion)) are needed to diagnose DH/TH lymphomas, while still missing those cases that carry a MYC-IGL translocation since no commercial probes are available for MYC-IGL fusion FISH." (PMID 34099699, 2021). "Moreover, lymphomas that have a concomitant translocation of MYC and BCL-2 or BCL-6 represent high-grade B-cell lymphoma and are resistant to conventional R-CHOP chemotherapy." (PMID 32296035, 2020). "Lymphomas that carry MYC and either a BCL2 or a BCL6 translocation (a double-hit lymphoma, DHL) or all three rearrangements (a triple-hit lymphoma, THL) are included in the current WHO classification as a new entity termed “High-grade B cell lymphomas with MYC and BCL2 and BCL6 rearrangements”." (PMID 32102485, 2020). "Although not widely surveyed, increased BCL6 protein levels were observed in solid tumors, implying that the tumorigenicity of BCL6 is not restricted to lymphomas." (PMID 31903146, 2020). "In terms of immunohistochemistry, expression of CD20 in lymphoma tissue could be detected in all patients, while only 32% (18/56) expressed CD10, 74% (34/46) Bcl-6, 65% (17/26) Bcl-2, and 66% (35/53) MUM1." (PMID 32160735, 2020). "Double/triple hit lymphoma (DH/TH), known as high-grade B-cell lymphoma (HGBL), is an aggressive diffuse large B cell lymphoma (DLBCL), defined as having concurrent MYC, BCL2, and/or BCL6 gene rearrangements." (PMID 33168821, 2020).
lymphoma (continued). "We show that DZNep inhibits proliferation and induces apoptosis of these cell lines independent of the type of lymphoma, the EZH2 mutation status and the MYC, BCL2 and BCL6 rearrangement status." (PMID 31419226, 2019). "The remaining 19 MYC rearranged patients, lacking an additional BCL2 or BCL6 translocation, were defined single hit lymphomas (SHL – MYC+/BCL2-/BCL6-)." (PMID 31976479, 2019). "“Double hit” lymphomas are characterized by the presence of both MYC and BCL-2 (or less commonly BCL-6) rearrangements, while “triple-hit” lymphomas demonstrate MYC, BCL-2, and BCL-6 rearrangements." (PMID 31115699, 2019). "Moreover, BCL6 and the BCOR-PRC1 complex containing FBXL10 are necessary for EZH2-driven GC formation and lymphoma precursor lesions." (PMID 29352142, 2018). "From the first defined decoy peptide mimicking the SMRT peptide that interacts with BCL6 and inhibits BCL6/SMRT PPI, other peptidomimetics were developed with interesting cellular activities and in vivo anti-lymphoma potencies as L-BPI or PR-BPI, F1324 or the cyclo-CIYYCV." (PMID 29921764, 2018). "Gfi1b has been identified as a retrovirus integration site in diffuse large B-cell lymphomas of mice containing the human BCL6 transgene, but this was not the case in retroviral injected non-transgenic control lymphomas." (PMID 28401061, 2017). "Of note, only 8% of cases harbored a MYC rearrangement and no cases of MYC/BCL2 or MYC/BCL6 double-hit lymphoma were identified." (PMID 28212447, 2017). "However, BCL6 inhibition also activates BCL6 target genes such as BCL2 and BCL2L1 (BCL-XL), and secondary MCL1, which can sustain lymphoma survival by suppressing the activity of pro-apoptotic BH3 proteins." (PMID 26657288, 2016). "Thus, most DLBCL cells require concomitant inhibition of BCL6 and BCL2-family members for effective lymphoma killing." (PMID 26657288, 2016). "Notably, DHLs or triple-hit lymphomas are classified in the new category of ‘high-grade B-cell lymphoma (HGBL), with rearrangements of MYC and BCL2 and/or BCL6’ in the 2016 updated WHO classification." (PMID 27606052, 2016). "Consequently, we showed that once BCL6 activity is suppressed, additional targeting of resistance mechanisms such as BCL2/BCL-XL/MCL1 provides superior anti-lymphoma effect." (PMID 26657288, 2016). "However BCL6 also directly represses several DLBCL oncogenes such as BCL2 and BCL-XL that promote lymphoma survival." (PMID 26657288, 2016). "More recently, MYC/BCL6 rearrangement lymphomas have been reported to be more frequently CD10 negative with IRF4/MUM1 positive, and cytogenetically less complex than MYC/BCL2 rearrangement lymphomas." (PMID 26416427, 2015). "Morphologically double hit lymphomas can have the appearance of BL, DLBCL, or follicular lymphoma whilst immunohistochemical studies suggest that the majority coexpress CD10, BCL6, and BCL2 and have a proliferation index between 50 and 100% as assessed by Ki67 staining." (PMID 25349747, 2014). "BCL6 interacts with co-repressor, SMRT, and this is essential for its role in lymphomas." (PMID 24595451, 2014). "The lymphoma cells in the 12 primary hepatic DLBCL cases were positive for the following antigens (number of positive cases, % of total): CD10 (4, 33.3%), Bcl2 (6, 50%), Bcl6 (5, 41.7%), MUM1 (5, 41.7%), and CD25 (5, 41.7%)." (PMID 22395482, 2012). "Cytogenetic characterization of these BCLu has shown that a proportion of them harbours a complex karyotype with two main genetic events—usually cMYC alterations together with BCL2 and/or BCL6, less commonly CCND1 rearrangements, designated the so-called “double hit” lymphomas (DHL)." (PMID 22548066, 2012). "Our data are compatible with the role of miR-205 in repression of BCL6 in normal tissue as expression of miR-205 was higher in thymus than in lymphoma tissues; in addition, miR-205 was virtually undetectable in EBV-negative lymphomas." (PMID 22870299, 2012).
lymphoma (continued). "Not surprisingly, both BCL6 and JAW1 were selected to be the significant prognostic predictors because of their importance involved in the underlying pathogenic mechanisms for lymphoma." (PMID 17888167, 2007). "The lymphomas that arose in founder 24 were histologically indistinguishable from typical line 17 lymphomas and like these were Pax5+ and BCL6- by immunostaining." (PMID 16563162, 2006). "The growth of lymphomas is typically supported by the expression of an anti-apoptotic protein; however, MMTV-RARαG303E lymphomas did not express BCL6, BCL2 or MCL1 (Results section), and preliminary data indicated that BCL-XL is weakly expressed." (PMID 16563162, 2006). "Also, BCL6 represses PRDM1, a critical factor of plasma cell differentiation, thereby maintaining B cells in an undifferentiated, proliferative state that contributes to lymphoma progression." (PMID 39815148, 2025). "In addition, new analysis predicted lymphoma subtypes using cell-of-origin markers that hematopathologists use in the clinical routine, including CD3, CD5, CD19, CD79A, MS4A1 (CD20), MME (CD10), BCL6, IRF4 (MUM-1), BCL2, SOX11, MNDA, and FCRL4 (IRTA1)." (PMID 38745770, 2024). "Most studies agree in recognizing that patients with DH lymphoma have lower survival than other DLBCL, while results are still controversial on the prognostic role of the isolated MYC translocation or immunohistochemical overexpression alone of MYC, BCL2, and/or BCL6 (DE lymphomas)." (PMID 38534887, 2024). "From a practical standpoint, HGBCL, nos are a diagnosis of exclusion in which a lymphoma with intermediate or blastoid cytomorphology and starry sky pattern triggers a “high grade” workup to exclude BL, HG/LBCL-11q, and HGBCL with MYC- and BCL2- and/or BCL6-rearrangement." (PMID 37530792, 2024). "Omomyc has been used in its transgenic form in BL, in murine lymphoma cell lines obtained from Eμ-myc transgenic mice and in Raji cells (wild-type or knock out for FBXO11) in vitro and in vivo (subcutaneous xenografts), alone or in combination with the BCL6 degrader BI-3802." (PMID 37457123, 2023). "Besides double-hit (DH) or triple-hit (TH) lymphomas, referring to translocations involving the MYC and BCL2 and/or BCL6 genes detected via FISH, the double-expressor (DE, assessed by IHC) lymphoma phenotype refers to strongly detectable protein expression of the MYC and BCL2 gene products." (PMID 35326604, 2022). "Immunohistochemistry of intrathoracic biopsy revealed that the tumor cells were positive for CD20, CD30, c-Myc, BCL-2, Mum-1, and PD-L1 but negative for CD3, CD5, CD10, BCL-6, PD-1, and cyclin D1, conforming to the pathological diagnosis of diffuse large B-cell lymphoma (DLBCL))." (PMID 33564306, 2021). "Expression of CD20 in lymphoma tissue could be detected in all patients by immunohistochemical analyses, while only 9% expressed CD5, 55% CD10, 9% CD30, 18% CD79a, 9% CD138, 82% BCL2, 55% BCL6 and 36% MUM1." (PMID 30340554, 2018). "Furthermore, because nodal MZLs are thought to arise from histogenetically heterogeneous subgroups of marginal zone cells, it is not surprising that a subset of these lymphomas express GC markers such as BCL6 and HGAL." (PMID 21988858, 2011). "Two recent reports have also implicated autoantigenic stimulation of B cells either in the genesis of a lymphoma that occurs in mice expressing a transgene for the TCL1 gene, and that resembles human B-CLL, or in the instance of DLBCL-like tumors that arose in Bcl-6 transgenic mice." (PMID 18578569, 2008). "Almost three in every five BCL6-rearranged double hit lymphoma cases in Taiwan are non-GCB phenotype, indicating, at least in part, that the preferential screening for double hit with BCL6 rearrangement may be a clinically-informative modality for patients with non-GCB phenotype DLBCL in Taiwan." (PMID 33807449, 2021).
lymphoma (continued). "Also, the mutation effects on TF binding at the promoter of two important FL genes (BCL6 and BCL2) were recovered: for example, regulatory activities of two TFs (FOXD2 and FOXD3) on BCL6 and BCL2 were confirmed previously by knockdown experiments in SUDHL4 lymphoma cell." (PMID 31001324, 2019). "Among DLBCL cases, 55 were germinal center B-cell-like (GCB) lymphoma 47 were non-GCB; 23 cases were double expressors (C-MYC and BCL2-positive), and 13 cases were found to be triple expressors (C-MYC, BCL-2, and BCL-6-positive]." (PMID 39759724, 2024). "“Quadruple-hit” lymphomas, while not a defined entity in either the WHO or ICC classification schema, have been characterized by the concurrent presence of MYC, BCL2, BCL6, and CCND1 rearrangements, and are extremely rare with an apparent dismal prognosis." (PMID 38914869, 2024). "Fluorescence in situ hybridization (FISH) analysis showed no rearrangements in BCL2, IRF4, or BCL6, and any deletion in the 1p36 region (TNFRSF14 gene), ruling out other lymphoma types." (PMID 39840177, 2024). "In contrast to DLBCL/HGBL-MYC/BCL2, aggressive lymphomas with either large cell or high-grade morphology and an MYC/BCL6 double hit, but lacking BCL2 translocations, form a heterogeneous tumor category without indications of a unifying biology." (PMID 37190213, 2023). "Nearly all lymphomas were of non-GCB phenotype (absence of CD10 in 13/14 cases, BCL6 + in 7/12 cases, MUM1 + in 19/19 cases)." (PMID 37098615, 2023). "DLBCL carrying genetic rearrangements of both MYC and BCL-2 genes, with or without a rearranged BCL-6 gene, were formerly known as double-hit (or triple-hit if BCL-6 is also involved) lymphomas." (PMID 37927464, 2023). "Immunohistochemistry stains of lymphoma cells were positive for CD20, CD79a, CD10, MUM1, BCL6, C-MYC, and negative for BCL2, cyclin D1, CD5, and CD3." (PMID 36120205, 2022). "Immunohistochemical analysis showed that the lymphoma expressed CD10, CD20, and BCL6 but was negative for CD34, BCL2, and TdT." (PMID 36171838, 2022). "In this new classification, the lymphoma subtype of this research is named diffuse large B-cell lymphoma/high-grade B-cell lymphoma with MYC and BCL2 rearrangements, and BCL6 is no longer included." (PMID 36497332, 2022). "The lymphoma cells were positive for CD20, BCL‐6, MUM1, MYC and BCL2, and were negative for CD3, CD5 and CD10, diagnostic of DLBCL, non‐GCB type." (PMID 36467806, 2022). "Lymphomas with two oncogenic translocations other than MYC (e.g. concomitant Bcl-2 and Bcl-6 translocations without a MYC breakpoint) or other gene translocations associated with MYC translocations (e.g. CCND1 translocations) are not included in this category." (PMID 36618391, 2022). "Another limitation was that the Swedish lymphoma register does not record molecular data, e.g. cell of origin, or MYC/BCL-2/BCL-6 translocations." (PMID 35999271, 2022). "There are two subgroups identified by gene expression profiling: (i) germinal centre B-cell-like (GCB) lymphomas (typically CD10+ and BCL6+), and (ii) non-GCB lymphomas that are developed from cells resembling activated B-cell-like lymphomas." (PMID 34360891, 2021). "Lymphoma cells were positive for CD20, CD10, Bcl‐2, Bcl‐6, cyclinD1, Ki67, c‐MYC and negative for CD30, CD5 and MUM‐1." (PMID 34698437, 2021). "In the 2017 WHO lymphoma classification, MYC/BCL6-DH DLBCL are included in the double-hit category, without any distinction from those with MYC/BCL2/BCL6-TH or MYC/BCL2-DH." (PMID 31844144, 2020). "Immunohistochemically, these lymphoma cells were positive for CD20, PAX-5, MUM-1, BCL-6 and CD5, but negative for CD3 and CD10." (PMID 32513269, 2020). "The double-expresser lymphomas have a worse outcome than other DLBCLs but they are not as aggressive as the HGBL, with rearrangements of MYC and BCL-2 and/or BCL-6." (PMID 31288832, 2019). "All CD19 negative lymphomas were positive for CD20, the majority was positive for PAX5, and two were positive for BCL2 and BCL6." (PMID 28484276, 2017).
lymphoma (continued). "The first group, “MYC-simple” is defined as lymphomas with immunoglobulin (IG)-MYC fusions and a low chromosomal complexity score (<6) that lacked IGH-BCL2 fusions and BCL6 breakpoints." (PMID 28379189, 2017). "The germinal center origin of the cells was supported by expression of CD10, BCL6, and/or HGAL, helping exclude lymphomas of non-germinal center origin." (PMID 26991267, 2016). "Rearrangement of BCL6 and MYC was detected in three patients, all of whom had nodal lymphomas with non-GC phenotypes." (PMID 24887414, 2014). "The results shows the B-cell lymphoma in study has Bcl-6 negative, CD10 negative and IRF4 positive phenotype, suggesting the lymphoma in study is a non-germinal center B-cell-like diffuse large B cell lymphoma." (PMID 22848504, 2012). "The lymphoma cells of all eight MALT lymphoma cases were positive for Bcl2 and negative for CD5, CD23, CD10, Bcl6, MUM1, and CD25." (PMID 22395482, 2012). "These lymphomas carry either IG-MYC fusion or non-IG-MYC fusion in combination with either BCL2 and/or BCL6 breaks." (PMID 22548066, 2012). "Consistently, lymphomas were Pax5+, B220+, CD43+, AA41+, CD69+ and negative for surface heavy or light chain immunoglobulins, CD5, CD4, CD8, CD23, CD21, BCL6." (PMID 16563162, 2006). "MMTV-RARαG303E lymphomas were high grade Pax-5+, surface H+L Ig negative, CD69+ and BCL6- and cytologically and phenotypically resembled human adult high grade (Burkitt's or lymphoblastic) lymphomas." (PMID 16563162, 2006). "Immunohistochemistry can aid distinction: lymphoma cells in FL usually co-express BCL2, CD10, and BCL6, but BCL2 alone is not specific, as reactive aggregates may also show positivity." (PMID 41181806, 2025). "There are rare cases where the translocation of MYC and BCL6 is present in the absence of BCL2 involvement (also defined as DH) and equally rare cases where all three translocations are present, a condition defined as “TH lymphomas”." (PMID 38534887, 2024). "Both in WHO-HAEM5 and the ICC, however, a fundamental change is that this entity comprises only cases with MYC and BCL2 rearrangements (DLBCL/HGBL-MYC/BCL2), with or without additional BCL6 breaks, so that aggressive lymphomas with dual rearrangements of MYC and BCL6 (without BCL2) are excluded." (PMID 37190213, 2023). "The third pathological investigation of the right paravascular iliac lesion indicated that the lymphoma had transformed into DLBCL (GCB subtype) that was negative for CD20 and positive for Bcl-6 (90%+), MUM1 (90%+), Ki-67 (80%+), Bcl-2 (90%+), c-myc (60%+), CD10 (+), and CD19(+)." (PMID 38143763, 2023). "Currently, HGBL is subgrouped as HGBL with MYC and Bcl-2 and/or Bcl-6 rearrangements, so-called double- or triple-hit lymphoma (HGBL-DH or HGBL-TH, respectively) and as HGBL, not otherwise specified (HGBL-NOS), which lacks MYC and Bcl-2 and/or Bcl-6 rearrangements." (PMID 35686130, 2022). "Therefore, the so-called “grey zone lymphomas” category has been removed and replaced with two new categories: “HGBL with MYC and BCL2 and/or BCL6 rearrangements”, or “HGBL-DH/TH”, and “HGBL not otherwise specified” (HGBL, NOS)." (PMID 34283060, 2021). "In addition, although MYC, BCL2 and BCL6 rearrangements are important prognostic markers for patients with DLBCL, the sensitivity of lymphoma cell lines to DZNep-mediated apoptosis is independent of these rearrangements." (PMID 31419226, 2019).